TNPO1P1 (transportin 1 pseudogene 1)
Gene: Processed pseudogene on chromosome 10 (84,390,908 to 84,392,045, forward strand). Ensembl gene ENSG00000225423.
Diseases named in the same sentence as TNPO1P1 in open-access papers:
TNPO1P1 is named in the same sentence as 1 disease in open-access papers, as found by Europe PMC text mining. Sharing a sentence is not in itself a finding about the gene and the disease. The quoted sentences say what the papers report.
ischemic stroke (1 paper, 2019). A stroke disorder caused by obstruction of blood flow to the brain, due to thrombotic (local blood clot formation) or embolic (due to a blood clot or other material traveling from another site) event. "Based on the qPCR results, three LncRNAs (SCARNA10, TERC, LINC01481) exhibited higher expression (p < 0.01), and three LncRNAs (FLJ23867, H3F3AP6, TNPO1P1) exhibited lower expression (p < 0.05) in ischemic stroke patient PBMCs than in healthy control PBMCs." (PMID 30774621, 2019).